STOX2 (storkhead box 2)
Synonyms: DKFZp762K222
Tractability: PROTAC: ubiquitination databases record sites on it; its protein half-life has been measured.
Gene: Protein-coding gene on chromosome 4 (183,797,692 to 184,023,526, forward strand). Ensembl gene ENSG00000173320.
Subcellular location (Human Protein Atlas): Cytosol; Nucleoplasm; Actin filaments
Gene Ontology:
Molecular function: DNA-binding transcription factor activity; RNA polymerase II transcription regulatory region sequence-specific DNA binding
Biological process: embryo development ending in birth or egg hatching; maternal placenta development; regulation of transcription by RNA polymerase II
Cellular component: cytoplasm; nucleus
Genetic constraint (gnomAD): Loss-of-function variants: 25 observed, 60.78 expected, observed/expected ratio (o/e) 0.41, 90% interval 0.3 to 0.57. The upper end of that interval is the gene's LOEUF score, 0.57, which puts it in group 2 of 6, group 1 being the genes least tolerant of losing a copy. Missense variants: 1,017 observed, 1,216.5 expected, observed/expected ratio (o/e) 0.84, 90% interval 0.79 to 0.88. Synonymous variants: 471 observed, 477.07 expected, observed/expected ratio (o/e) 0.99, 90% interval 0.92 to 1.07.
Homologues: Orthologues: chimpanzee STOX2 (100% identical), macaque STOX2 (99% identical), mouse Stox2 (96% identical), pig STOX2 (95% identical), rabbit STOX2 (94% identical), dog STOX2 (92% identical), rat Stox2 (91% identical), guinea pig STOX2 (89% identical), tropical clawed frog stox2 (76% identical), zebrafish stox2a (63% identical), zebrafish stox2b (57% identical), Drosophila melanogaster CG33285 (5% identical). Paralogues in human: STOX1 (25% identical).
Diseases named in the same sentence as STOX2 in open-access papers:
STOX2 is named in the same sentence as 15 diseases in open-access papers, as found by Europe PMC text mining. Sharing a sentence is not in itself a finding about the gene and the disease. The quoted sentences say what the papers report.
fetal growth restriction (3 papers, 2016 to 2022). A fetus that does not grow beyond the 10th percentile of conventionally accepted weight for gestational age. "Storkhead box protein 2 (STOX2) is a transcriptional factor associated with pre-eclampsia with fetal growth restriction." (PMID 27050375, 2016). "Moreover, STOX2 expression was reduced in the decidual tissue of patients with fetal growth restriction (FGR)." (PMID 27050375, 2016). "Storkhead box protein 2 (STOX2) is considered a transcriptional factor, and its expression is decreased in the decidual tissue of patients with fetal growth restriction." (PMID 30115834, 2018).
oral squamous cell carcinoma (2 papers, 2016 to 2020). "STOX2 has been associated with pre-eclampsia and oral squamous cell carcinomas." (PMID 33339109, 2020).
preeclampsia (2 papers, 2011 to 2022). Preeclampsia is a hypertensive disorder of pregnancy that is characterized by new-onset hypertension with proteinuria presenting after 20 weeks of gestation, and depending on mild or severe forms may initially present with severe headache, visual disturbances, and hyperreflexia. "Storkhead box 2 is a winged helix domain protein, encoded by the STOX2 gene on chromosome 4q35, near the chromosomal region associated with preeclampsia." (PMID 35246136, 2022). "The STOX2 gene on chromosome 4q35 is located in close proximity to a chromosomal area (4q31-4q32) that has been implicated in preeclampsia in different populations (Finland, Australia, and New Zealand) as well." (PMID 21490791, 2011). "However, the latest data including those from independent groups not only confirm the role of STOX1 in trophoblast dysfunction underlying preeclampsia but also indicate a role for its paralog, STOX2." (PMID 21490791, 2011). "Interestingly, as a comparable function to STOX1, which shows a gain-of-function is suggested, and STOX2 is downregulated in preeclampsia samples, compatible with a loss-of-function, this would indicate that these two genes have similar functions but opposite effects in placental function." (PMID 21490791, 2011). "Interestingly, a significant difference was observed for STOX2 gene expression when healthy decidua samples were compared to decidua samples that suffered from preeclampsia complicated by IUGR, where the preeclampsia samples showed a lower expression of STOX2 compared to controls." (PMID 21490791, 2011).
breast carcinoma (1 paper, 2022). "We will therefore concentrate our future efforts on the elucidation of the mechanism by which LOX induces expression of the STOX2 gene and on the elucidation of the role of STOX2 in the biological responses to LOX expression in breast cancer cells and normal cells." (PMID 36232621, 2022).
colon adenoma (1 paper, 2016). An adenoma that arises from the colon. "Conversely, CpG island hypermethylation of STOX2 promoter region reportedly reduces STOX2 expression in colon adenoma and adenocarcinoma." (PMID 27050375, 2016).
gastric cancer (1 paper, 2025). A primary or metastatic malignant neoplasm involving the stomach. "While EFEMP1 (HR = 1.94, 95% CI 1.27–2.97, p < 0.001), ANKRD29 (HR = 1.77, 95% CI 1.28–2.44, p < 0.001), and STOX2 (HR = 1.50, 95% CI 1.08–2.07, p = 0.014) are all associated with a positive prognostic value for gastric cancer patients." (PMID 41367615, 2025). "Among 20 shared core genes across disease stages, 13 genes (e.g., FCRL3,EFEMP1,ANKRD29,STOX2) were identified as unfavorable prognostic factors for gastric cancer." (PMID 41367615, 2025). "FCRL3, EFEMP1, ANKRD29, and STOX2 may serve as potential biomarkers for monitoring the transition from precancerous lesions to gastric cancer, offering insights into the mechanisms of gastric carcinogenesis and supporting early diagnosis and intervention strategies." (PMID 41367615, 2025).
hydatidiform mole (1 paper, 2022). A gestational trophoblastic disorder characterized by marked enlargement of the chorionic villi, hyperplasia of the villous trophoblastic cells and hydropic changes. "In the present study, based on the observation of the low expression of miR-30a in hydatidiform mole tissue, we combined laboratory database and biological software prediction to identify STOX2 as a possible target of miR-30a." (PMID 35246136, 2022). "Further research into the specific molecular mechanism of this process is required, which could lead to new treatment strategies for hydatidiform moles by targeting miR-30a and STOX2." (PMID 35246136, 2022). "In the summary, we demonstrated that STOX2 is highly regulated in hydatidiform moles." (PMID 35246136, 2022). "miR-30a targets the 3′ UTR of STOX2 mRNA and has low expression in hydatidiform moles." (PMID 35246136, 2022). "In the present study, we found that STOX2 not only reduced cell proliferation and metastasis, but also was highly expressed in hydatidiform mole tissues, which suggested that STOX2 might induce hydatidiform moles." (PMID 35246136, 2022). "In the present study, we found that the expression of STOX2 was high in hydatidiform mole tissues." (PMID 35246136, 2022). "Further experiments showed that miR-30a, by regulating STOX2, actives the protein kinase B (AKT), ERK, and P38 signaling pathways to affect the development of hydatidiform moles." (PMID 35246136, 2022).
polydactyly (1 paper, 2024). A disease characterized by the presence of polydactyly, including syndromic and non-syndromic forms. "Combined with the results of genome-wide association studies, we identified candidate genes associated with the crest (SMYD and STOX2) and polydactyly (SLC52A3 and ANGPT4)." (PMID 38612286, 2024).
tumor (2 papers, 2016 to 2022). "Further in vitro/in vivo analysis and large-scale clinicopathological investigations using OSCC and non-tumor oral mucosa will be required to define the methylation and promoter activity of STOX2." (PMID 27050375, 2016). "AGR2 and STOX2 were previously identified as promoters of tumor progression." (PMID 36232621, 2022). "Although cancer stromal STOX2 may improve host anticancer immunity, further studies will be required to validate the role of STOX2 in tumor stroma." (PMID 27050375, 2016). "Notably, the expression of STOX2 and AGR2 had been previously linked to tumor progression." (PMID 36232621, 2022). "Further investigations into STOX2 may provide new insights into molecular tumor markers of OSCC." (PMID 27050375, 2016).
STOX2 also shares sentences with these, for which no sentence is quoted: adenocarcinoma (1 paper); cancer (1); colon cancer (1); glioblastoma (1); melanoma (1); thalassemia (1).